RFC2 (replication factor C subunit 2)
Description:
Subunit of the replication factor C (RFC) complex which acts during elongation of primed DNA templates by DNA polymerases delta and epsilon, and is necessary for ATP-dependent loading of proliferating cell nuclear antigen (PCNA) onto primed DNA. This subunit binds ATP (By similarity).
Synonyms: RFC40; A1
Tractability: Small molecule: a structure with a bound ligand is known. PROTAC: ubiquitination databases record sites on it; its protein half-life has been measured.
Gene: Protein-coding gene on chromosome 7 (74,223,231 to 74,254,458, reverse strand). Ensembl gene ENSG00000049541.
Subcellular location: Nucleus
Subcellular location (Human Protein Atlas): Nucleoplasm; Golgi apparatus
Pathways (Reactome):
DNA Repair: Dual Incision in GG-NER; Dual incision in TC-NER; Gap-filling DNA repair synthesis and ligation in GG-NER; Gap-filling DNA repair synthesis and ligation in TC-NER; HDR through Homologous Recombination (HRR); HDR through Single Strand Annealing (SSA); PCNA-Dependent Long Patch Base Excision Repair; Presynaptic phase of homologous DNA pairing and strand exchange; Processing of DNA double-strand break ends; Recognition of DNA damage by PCNA-containing replication complex; Termination of translesion DNA synthesis; Translesion Synthesis by POLH; Translesion synthesis by POLI; Translesion synthesis by POLK; Translesion synthesis by REV1
Cell Cycle: Activation of ATR in response to replication stress; G2/M DNA damage checkpoint; Polymerase switching on the C-strand of the telomere
DNA Replication: Polymerase switching
Disease: Impaired BRCA2 binding to RAD51
Gene Ontology:
Molecular function: DNA clamp loader activity; protein binding; single-stranded DNA helicase activity; ATP binding; ATP hydrolysis activity; DNA binding; enzyme binding
Biological process: DNA-templated DNA replication; positive regulation of DNA-directed DNA polymerase activity; DNA repair; DNA replication; DNA replication checkpoint signaling
Cellular component: Ctf18 RFC-like complex; DNA replication factor C complex; nucleoplasm; Rad17 RFC-like complex; Elg1 RFC-like complex; nucleus; chromosome
Genetic constraint (gnomAD): Loss-of-function variants: 10 observed, 12.14 expected, observed/expected ratio (o/e) 0.82, 90% interval 0.51 to 1.39. The upper end of that interval is the gene's LOEUF score, 1.39, which puts it in group 5 of 6, group 1 being the genes least tolerant of losing a copy. Missense variants: 185 observed, 193.99 expected, observed/expected ratio (o/e) 0.95, 90% interval 0.85 to 1.08. Synonymous variants: 94 observed, 82.56 expected, observed/expected ratio (o/e) 1.14, 90% interval 0.96 to 1.35.
Homologues: Orthologues: chimpanzee RFC2 (99% identical), pig RFC2 (94% identical), dog RFC2 (94% identical), mouse Rfc2 (92% identical), guinea pig RFC2 (92% identical), rat Rfc2 (92% identical), rabbit RFC2 (90% identical), tropical clawed frog rfc2 (84% identical), zebrafish rfc2 (83% identical), Drosophila melanogaster RfC4 (68% identical), macaque RFC2 (66% identical), Caenorhabditis elegans rfc-2 (56% identical). Paralogues in human: RFC5 (35% identical), RFC4 (34% identical), RFC3 (24% identical).
Diseases named in the same sentence as RFC2 in open-access papers:
RFC2 is named in the same sentence as 53 diseases in open-access papers, as found by Europe PMC text mining. Sharing a sentence is not in itself a finding about the gene and the disease. The quoted sentences say what the papers report.
colorectal cancer (7 papers, 2021 to 2024). A primary or metastatic malignant neoplasm that affects the colon or rectum. "Recently, it has been increasingly reported that the high expression of RFC2 is associated with the proliferation, migration, and invasion of colorectal cancer and hepatocellular carcinoma." (PMID 37251536, 2023). "As tumor suppressor microRNA, miR-744 inhibited the proliferation of colorectal cancer cells by targeting RFC2." (PMID 36922987, 2023). "For instance, RFC2, targeted by miR-744, regulates the cell cycle and proliferation of colorectal cancer cells." (PMID 35791074, 2022). "For instance, RFC2 expression was elevated in colorectal cancer (CRC) tissues and related to aggressive CRC clinicopathological symptoms, and its knockdown significantly suppressed the proliferation of CRC cells." (PMID 35210438, 2022). "Existing studies have shown that RFC2 is significantly upregulated in some tumors, such as nasopharyngeal carcinoma, choriocarcinoma, and colorectal cancer." (PMID 34022962, 2021). "Our study investigated the roles of RFC2 in colorectal cancer (CRC)." (PMID 37821801, 2023). "The results showed that RFC2 was generally highly expressed in many types of cancer tissues compared with normal tissues, including brain and CNS cancer, colorectal cancer, gastric cancer, head and neck cancer, kidney cancer, myeloma, ovarian cancer, sarcoma, and other cancer." (PMID 35210438, 2022). "In colorectal cancer tissues, the staining levels of RFC1, RFC2, RFC4, and RFC5 protein expression were modest." (PMID 38504096, 2024).
glioma (6 papers, 2022 to 2025). A benign or malignant brain and spinal cord tumor that arises from glial cells (astrocytes, oligodendrocytes, ependymal cells). "For instance, FoxO1 promotes glioma cell proliferation by acting as a transcriptional activator of RFC2." (PMID 37821801, 2023). "Another novel glioma biomarker relevant to the immune microenvironment is replication factor 2 (RFC2), a subunit of the RFC complex that modulates DNA replication and repair." (PMID 36425564, 2022).
hepatocellular carcinoma (6 papers, 2021 to 2025). A malignant tumor that arises from hepatocytes. "RFC2 is overexpressed in hepatocellular carcinoma (HCC) and is associated with advanced stages of the disease and poor survival outcomes." (PMID 40980067, 2025). "Other studies have shown that high expression of RFC2 is associated with poor survival in CRC, glioblastoma, and hepatocellular carcinoma and aids in predicting breast cancer progression and metastasis." (PMID 38504096, 2024). "RFC2 plays an oncogenic role in progression of hepatocellular carcinoma by regulating DNA replication and cell cycle." (PMID 37821801, 2023). "Previous experimental studies have shown that RFC2 is highly expressed in various cancer, such as sarcoma, diffuse lower-grade gliomas, hepatocellular carcinoma, and CRC." (PMID 37821801, 2023). "Similarly, high expression of RFC2 is related to worse overall survival of hepatocellular carcinoma." (PMID 37821801, 2023).
glioblastoma (4 papers, 2017 to 2024). The most malignant astrocytic tumor (WHO grade IV). "Meanwhile, other studies have shown that the expression level of RFC2 was also higher in the normal tissues than in patients with glioblastoma." (PMID 35483337, 2022). "Previous studies have found that the inhibition of RFC2 can enhance the cytotoxicity of temozolomide to glioblastoma." (PMID 34022962, 2021). "A total of 5 key DNA repair genes, CDK7, DDB2, RNH1, RFC2 and FAH, were screened to be significantly related to the prognosis of glioblastomas (p = 9.74e−05)." (PMID 28938550, 2017).
nasopharyngeal carcinoma (4 papers, 2014 to 2024). A carcinoma arising from the nasopharyngeal epithelium. "Studies have shown that RFC2 was significantly up-regulated in some tumor tissues, such as nasopharyngeal carcinoma (NPC) tissue and choriocarcinoma tissue." (PMID 34022962, 2021). "For example, amplification of RFC3 is frequently found in esophageal adenocarcinoma, while RFC2 is overexpressed in nasopharyngeal carcinoma." (PMID 25407051, 2014).
Williams syndrome (4 papers, 2009 to 2024). "RFC2 is famous for DNA replication and damage repair, and participates in disorder of biological process, such as Williams-Beuren syndrome, type 2 diabetes mellitus, and cancers." (PMID 37821801, 2023).
breast carcinoma (3 papers, 2008 to 2024). "Previous studies have shown that RFC2 is related to the progression and metastasis of breast cancer and can be used as a prognostic indicator for breast cancer patients." (PMID 34022962, 2021).
liver cancer (3 papers, 2021 to 2022). An epithelial or non-epithelial malignant neoplasm that arises from the liver. "In this study, the expression of RFC2 mRNA is significantly related to the clinical stage and tumor grade of liver cancer." (PMID 34022962, 2021). "In this study, the expression, function, interaction pathway and prognostic value of RFC2 in HCC were analyzed for the first time to guide the future research of liver cancer." (PMID 34022962, 2021). "The mRNA expression of RFC2 was significantly correlated with the prognosis of liver cancer patients." (PMID 34022962, 2021). "The mRNA expression of RFC2 was significantly upregulated in primary liver cancer tissues compared with normal samples (p < 0.05)." (PMID 34022962, 2021). "In order to solve this problem, the expression of RFC2 in liver cancer patients was analyzed through ONCOMINE, UALCAN, Human Protein Atlas." (PMID 34022962, 2021). "The mRNA expression of RFC2 was found to be markedly higher in liver cancer tissues in the data set." (PMID 34022962, 2021). "Studies have shown that RFC2 could regulate the cell cycle and DNA replication process to promote liver cancer development and could act as an oncogene in the progression of lower-grade gliomas." (PMID 36189312, 2022). "In addition, the function of RFC2 in liver cancer is DNA replication, and the main mechanism is cell cycle phase transition." (PMID 34022962, 2021). "Furthermore, the function of RFC2 in liver cancer was DNA replication, and its main mechanism was the phase transition of the cell cycle." (PMID 34022962, 2021). "RFC2 might promote the development of liver cancer, which might be achieved by regulating cell cycle and DNA replication." (PMID 34022962, 2021). "Besides, the protein expression of RFC2 was explored in liver cancer through the Human Protein Atlas (HPA)." (PMID 34022962, 2021). "In general, the transcription and protein of RFC2 are overexpressed in patients with liver cancer." (PMID 34022962, 2021). "In addition, in patients with liver cancer, higher RFC2 expression was found to be significantly correlated with shorter OS and DFS." (PMID 34022962, 2021). "The JHH7 and HEPG2 cell line may be suitable for the study of the mechanism of RFC2 in liver cancer." (PMID 34022962, 2021). "Additionally, RFC2 was found to modulate the cell cycle and DNA replication of liver cancer." (PMID 35791074, 2022). "RFC2 may be a prognostic biomarker for the survival of liver cancer patients." (PMID 34022962, 2021). "Secondly, the potential diagnostic and therapeutic role of RFC2 in liver cancer has not been evaluated, so further studies are needed to explore whether RFC2 can be used as a diagnostic marker or therapeutic target." (PMID 34022962, 2021).
sarcoma (3 papers, 2022 to 2023). A usually aggressive malignant neoplasm of the soft tissue or bone. "Moreover, Gene Expression Profiling Interactive Analysis (GEPIA) and Kaplan-Meier Plotter showed that highly expressed RFC2-5 were associated with poor overall survival (OS) or relapse-free survival (RFS) in sarcoma patients." (PMID 35483337, 2022). "Meanwhile, in the analysis of GEPIA and Kaplan Meier plotter, we also found that patients with sarcoma with high expression of RFC2 had poor disease-free survival (DFS), which was statistically significant." (PMID 35483337, 2022). "The results, however, of the database suggested that high expression of RFC2 and RFC4 were associated with the poor DFS and RFS in sarcoma, with statistical differences." (PMID 35483337, 2022). "Expression levels of RFC2-5 have a predictive effect on the total survival (OS) or disease-free survival (DFS) of sarcoma patients." (PMID 35483337, 2022). "Therefore, RFC2 not only plays an oncogene role in fibrosarcoma but also has a latent function in predicting disease outcomes in sarcoma." (PMID 35483337, 2022). "Through the CCLE database, we found that RFC2 was also up-regulated in sarcoma cell lines." (PMID 35483337, 2022). "Therefore, transcription of RFC2-5 is a potential prognostic marker for improving survival and prognostic accuracy in sarcoma patients." (PMID 35483337, 2022). "According to reports, RFC2 is one of the important components of the RFC complex that can unload PCNA and inhibit DNA polymerase activity, it is highly expressed in some sarcoma tissues and cells." (PMID 35483337, 2022). "The results showed that RFC2, RFC4, and RFC5 were upregulated in sarcoma patients, while the high expression levels of RFC1 and RFC3 were both with no significance." (PMID 35483337, 2022). "In addition, Cancer Cell Line Encyclopedia (CCLE) dataset analysis indicated that RFC1, RFC2, RFC3, RFC4, and RFC5 were elevated expressed in sarcoma cell lines." (PMID 35483337, 2022). "Similarly, we found that mRNA expression levels of RFC2, RFC3, RFC4, and RFC5 from RFC family genes were upregulated in sarcoma tissues." (PMID 35483337, 2022).
choriocarcinoma (2 papers, 2021 to 2022). An aggressive malignant tumor arising from trophoblastic cells. "There was a study pointed out that in patients with choriocarcinoma, high expression of RFC2 may have the effect of predicting the prognosis of the disease." (PMID 35483337, 2022).
Fanconi anemia (2 papers, 2021 to 2023). Fanconi anemia (FA) is a hereditary DNA repair disorder characterized by progressive pancytopenia with bone marrow failure, variable congenital malformations and predisposition to develop hematological or solid tumors. "Among these genes were members of the Fanconi anemia (FA) core complex (Fanca, Fancc, and Fancl), Rad51, Mlh1, Atrip, and Rfc2; all were expressed at significantly higher levels in Ncf1–/– vs. WT NSCs." (PMID 36707536, 2023).
acute myeloid leukemia (1 paper, 2022). Acute myeloid leukemia (AML) is a group of neoplasms arising from precursor cells committed to the myeloid cell-line differentiation. "In contrast, the RFC2 gene had a much lower expression in acute myeloid leukemia (LAML)." (PMID 35210438, 2022).
Anxiety (1 paper, 2024). Intense feelings of nervousness, tension, or panic often arise in response to interpersonal stresses. "Compared to WT siblings, heterozygous rfc2 KO adult zebrafish traveled a shorter distance and spent less time in the light zone, indicating increased anxiety." (PMID 39368701, 2024). "In addition, heterozygous rfc2 KO adult zebrafish demonstrate an anxiety-like behavior with increased social cohesion." (PMID 39368701, 2024). "Furthermore, the heterozygous rfc2 KO zebrafish exhibited significant behavioral changes, especially a reduction in movement and increased anxiety-like behavior, suggesting a possible involvement of RFC2 haploinsufficiency in neurodevelopmental disorders." (PMID 39368701, 2024). "Furthermore, behavioral impairment in heterozygous rfc2 KO adults, especially reduced movement, can be attributed to either defects in physical motor activity or psychiatric issues, such as anxiety." (PMID 39368701, 2024).
astrocytoma (1 paper, 2022). "Based on WHO grade and pathological classification, a distinctively elevated expression of RFC2 was observed in LGG patients with WHO III grade (P < 0.001) and astrocytoma (P = 0.025 and P = 0.00067 respectively)." (PMID 35210438, 2022). "Moreover, RFC2 expression was obviously increased in LGG samples with WHO III grade (P < 0.001), astrocytoma (P = 0.041 and P = 0.023), and IDH1 wild-type (P < 0.001)." (PMID 35210438, 2022).
brain tumor (1 paper, 2022). "The immunohistochemistry staining results showed that RFC2 was primarily localized in the nucleus, and RFC2 was significantly highly expressed in LGG tissues than that in benign brain tumor tissues." (PMID 35210438, 2022). "To further confirm the potential oncogenic role of RFC2 in LGG, we examined RFC2 expression and performed a clinical correlation analysis of RFC2 in our LGG samples, which contained 69 LGG tissues and 10 benign brain tumor tissues." (PMID 35210438, 2022).
cognitive defects (1 paper, 2024). "Thus, heterozygous loss of RFC2 may also be relevant when explaining cognitive defects observed in WS patients." (PMID 39368701, 2024).
diffuse large B-cell lymphoma (1 paper, 2022). "The Cox proportional hazards model analysis revealed that the expression levels of RFC2 were correlated with the OS in ACC, lymphoid neoplasm diffuse large B-cell lymphoma (DLBC), GBM, KICH, KIRP, LAML, LGG, LIHC, LUAD, mesothelioma (MESO), PAAD, thymoma (THYM), UCEC, and ocular melanomas (UVM)." (PMID 35210438, 2022).
Encephalopathy (1 paper, 2024). Encephalopathy is a term that means brain disease, damage, or malfunction. "Patients with WS frequently exhibit features like microcephaly or encephalopathy and reduced head and brain size, which mirrors the phenotypes observed in both rfc2 and rfc5 KO zebrafish." (PMID 39368701, 2024).
Ewing sarcoma (1 paper, 2022). A small round cell tumor that lacks morphologic, immunohistochemical, and electron microscopic evidence of neuroectodermal differentiation. "Some evidence suggested that RFC2 was a key gene, and its upregulation was related to the metastasis and prognosis of Ewing’s sarcoma." (PMID 35483337, 2022). "RFC2, as a key gene, was upregulated in metastatic samples from Ewing's sarcoma patients." (PMID 35483337, 2022).
fibrosarcoma (1 paper, 2022). A malignant mesenchymal fibroblastic neoplasm affecting the soft tissue and bone. "In Detwiller Sarcoma’s dataset, RFC2, with a fold change of 3.287, was overexpressed in Fibrosarcoma." (PMID 35483337, 2022). "In our study, the expression of RFC2 in fibrosarcoma was 3.287 times higher than in normal tissues." (PMID 35483337, 2022).
Intellectual disability (1 paper, 2024). "Furthermore, we identified one patient with a smaller 167.21-kb microdeletion within the WSCR, including EIF4H, LAT2, RFC2, and CLIP2, but not comprising the ELN gene and segregating in the family with non-syndromic intellectual disability." (PMID 39368701, 2024).
lung carcinoma (1 paper, 2017). "After removing 20% of expression data via the MCAR mechanism, the expression profile for RFC2 in lung cancer cells was similar to that of the original dataset." (PMID 29247873, 2017).
microcephaly (1 paper, 2024). A congenital or acquired developmental disorder in which the circumference of the head is smaller than normal for the person's age and sex. "We observed apoptosis in the same regions where rfc2 and rfc5 are expressed, suggesting that DNA damage-induced apoptosis during brain development might underlie the microcephaly phenotype in KOs." (PMID 39368701, 2024).
Obesity (1 paper, 2018). Accumulation of substantial excess body fat. "Two genes related to obesity, STX1A and RFC2, map to this CNV interval." (PMID 29441128, 2018).
paraganglioma (1 paper, 2022). A benign or malignant neoplasm arising from paraganglia located along the sympathetic or parasympathetic nerves. "Additionally, the Cox proportional hazards model of PFI revealed that the elevated expression of RFC2 predicted a poor PFI in ACC, KICH, KIRC, KIRP, LGG, MESO, PAAD, pheochromocytoma & paraganglioma (PCPG), PRAD, SARC, UCEC, and UVM." (PMID 35210438, 2022).